BRAF (B-Raf proto-oncogene, serine/threonine kinase)
Diseases named in the same sentence as BRAF in open-access papers (continued):
Sharing a sentence is not in itself a finding about the gene and the disease.
melanoma (continued). "ALDH2-low metastatic melanoma cells exhibited intrinsic resistance to BRAF and MEK inhibitors, a phenomenon confirmed in ALDH2-KO A375 cells." (PMID 40558540, 2025). "Our findings not only help explain how BRAF-mutant melanoma survives the acute phases of MAPK inhibition, they also highlight an emerging theme of pro-invasive small GTPases that link mechanisms of tumorigenesis to drug resistance." (PMID 40909781, 2025). "To date, no randomized trials have directly compared adjuvant BRAF/MEK inhibition with anti-PD-1 therapy in patients with BRAF-mutant stage III or resected stage IV melanoma." (PMID 40758471, 2025). "Melanoma resistance to molecular targeted therapy was observed after implementing BRAF inhibitors into clinical practice." (PMID 40636307, 2025). "Genetic mutation, especially in the BRAF, NRAS, and CDKN2A genes, plays a very significant part in the development of melanoma." (PMID 41049012, 2025). "The term corresponding compound vemurafenib is a BRAF inhibitor used as a targeted therapy for Erdheim-Chester disease and melanoma." (PMID 39872221, 2025). "In BRAF-mutant melanoma, pharmacologic induction of gasdermin D/E-mediated pyroptosis has demonstrated synergy with BRAF/MEK inhibition in resistant models, eliciting immunogenic cell death and potentiating anti-tumor immunity." (PMID 40909289, 2025). "BRAF inhibitors are available for patients with aggressive BRAF-mutant melanoma that has progressed following prior immunotherapy, as it enhances response rates and extends both progression-free and overall survival." (PMID 39795195, 2025). "Currently, interest in SPARC is growing as its expression levels in melanoma tumors show good predictive value for anticipating the emergence of chemoresistance to BRAF/MEK-inhibitor therapies." (PMID 40943659, 2025). "This improvement not only boosts treatment efficacy but also increases the ORR from 45% to 68% in BRAF-mutant melanoma." (PMID 41301459, 2025). "We focused the analysis on lipid metabolism pathways showing significant dysregulation in melanoma resistance to BRAF/MEKi in our previous studies." (PMID 41550951, 2025). "Targeted therapies, such as BRAF/MEK inhibitors in melanoma and TKIs in HCC, modulate immune responses, resulting in tumor susceptibility to checkpoint blockade." (PMID 40361336, 2025). "In BRAF-mutant melanoma, monotherapy with BRAF inhibitors has shown an overall survival (OS) of 13.6 months, progression-free survival (PFS) of 6.9 months, and an objective response rate (ORR) of 48%." (PMID 40896440, 2025). "DNA NGS testing at our institution revealed a BRAF wild-type, NRAS G12D-mutation-positive melanoma consistent with his original molecular report, prior to the melanoma." (PMID 39940799, 2025). "Among the most established therapies targeting the BRAFV600E mutation site are vemurafenib (approved in 2011) and dabrafenib (approved in 2013), which serve as first-line treatments for advanced BRAF-mutant melanoma." (PMID 40932870, 2025). "For V600E mutations in NSCLC, following the successful application of double BRAF/MEK inhibition in melanoma, two phase II trials with dabrafenib and trametinib were conducted on pretreated and treatment-naive patients with metastatic lung adenocarcinoma." (PMID 40332392, 2025). "A375 cells have been chosen as a model of melanoma, in which we previously demonstrated that oncogenic BRAF supports ERK5 nuclear localization in routinely cultured cells, thus supporting cell proliferation." (PMID 38965815, 2025). "For instance, mutations in the BRAF, NRAS, and KIT genes are well-documented in human melanomas, leading to constitutive activation of the MAPK pathways promoting tumorigenesis." (PMID 41394861, 2025). "Other studies also confirm a lower rate of BRAF and NRAS mutations in spitzoid melanoma compared to other melanoma subtypes." (PMID 39415471, 2025).
melanoma (continued). "Among these, only the combination of dabrafenib/trametinib is approved as adjuvant therapy in fully resected stage III BRAF V600-mutant melanoma subjects." (PMID 40872623, 2025). "The median age was 63 years in the BRAFWT melanoma group, whereas it was 51 years in the BRAF-mutant melanoma group." (PMID 41010758, 2025). "Resistance to dabrafenib and trametinib in BRAF-mutant melanoma has been widely investigated, revealing diverse mechanisms." (PMID 41008893, 2025). "The trunk was the most frequent anatomical site in our series (27.5%), consistent with previous reports in BRAF-mutant melanoma where this location predominates over the extremities and head and neck." (PMID 40994966, 2025). "This approach is particularly relevant given the emerging recognition of sarcoidosis-like reactions as immune-related adverse events in melanoma patients receiving checkpoint inhibitors or BRAF/MEK targeted therapies." (PMID 41409940, 2025). "In melanomas, Class I MAP2K1 mutations have been identified as secondary oncogenic drivers, typically occurring alongside BRAF, NRAS, or NF1 mutations." (PMID 40107205, 2025). "A randomized trial comparing dabrafenib + trametinib in combination with either hydroxychloroquine or placebo in patients with BRAF V600 mutant melanoma (NCT04527549) terminated early due to slow accrual." (PMID 40457397, 2025). "Large-scale genomic sequencing of melanoma has identified bona fide activating mutations in RAC1, which are associated with resistance to BRAF-targeting therapies." (PMID 39636745, 2025). "The expression levels were higher in SR compared to LR samples, indicating the association between a high expression of the miR-99b~125a~let-7e cluster with a reduced sensitivity to BRAF/MEKi of melanoma tumors." (PMID 41550951, 2025). "Cancer cells, especially BRAF mutant melanomas, have been shown to shift toward glycolytic metabolism even in the presence of functional oxidative phosphorylation." (PMID 40135438, 2025). "One such approach involves the use of the caspase-3 activator raptinal, which induces pyroptosis in BRAF-mutant melanoma through GSDME cleavage." (PMID 41235238, 2025). "Given the similarities between drug tolerance and cellular dormancy, we studied the dormancy marker, nuclear receptor subfamily 2 group F member 1 (NR2F1), in response to BRAF-V600E inhibitors (BRAFi) plus MEK inhibitors (MEKi) in BRAF-mutant melanoma models." (PMID 40955663, 2025). "In the Checkmate 067 trial, patients with unresectable Stage III and IV melanoma with known BRAF status were randomized to either Ipilimumab plus Nivolumab, Nivolumab monotherapy or Ipilimumab monotherapy." (PMID 41342263, 2025). "As expected, based on published activity in BRAF fusion models, daily administration of tovorafenib at clinically relevant doses resulted in tumor regression in the AGK::BRAF fusion melanoma model." (PMID 40111124, 2025). "While surgical excision is effective for localized tumours, the management of advanced melanoma has been revolutionized by targeted therapies, such as BRAF-MEK inhibitors, and by immune checkpoint inhibitors, which have significantly improved patient survival." (PMID 41030783, 2025). "Vemurafenib, a BRAF inhibitor, induces ER stress in BRAF-mutant melanoma when combined with RAF/MEK/ERK (MAPK) pathway inhibition, promoting cell death." (PMID 40331942, 2025). "In BRAF inhibitor-resistant melanoma cells, small molecules such as the Caspase-3 agonist raptinal reversed the resistant phenotype by restoring GSDME expression, significantly enhancing tumor cell sensitivity to chemotherapeutic agents." (PMID 40497999, 2025). "Recently, we demonstrated that PMCA4b over-expression induced cell polarization and actin cytoskeleton remodeling of BRAF mutant melanoma cells." (PMID 40075218, 2025). "Our study is the first to evaluate this therapeutic combination in BRAF and non-BRAF mutant melanoma lines, demonstrating a general mechanism of resistance through a metabolic switch." (PMID 40943167, 2025).
melanoma (continued). "Previous studies on BRAF‐ and NRAS‐mutated melanomas have identified the co‐occurrence of mutations affecting members of this critical pathway." (PMID 41017066, 2025). "Among these resistant melanomas, BRAF splicing is one of the most frequently occurring driving events, with a recurrence rate of 31.58%, underscoring the potential contribution of alternative splicing to drug tolerance." (PMID 40681872, 2025). "Mutations in upstream components such as RAS or BRAF (e.g., the V600E mutation) can lead to constitutive ERK activation, promoting uncontrolled cell proliferation in cancers such as melanoma." (PMID 40547482, 2025). "Patient 1, a male in his 30s with BRAF V600E-mutant melanoma, was initially treated with ipilimumab and nivolumab upon diagnosis of widespread metastatic disease." (PMID 40264106, 2025). "DNA-based assays, including targeted gene panels and sequencing technologies, have enabled biomarker-driven therapies in many malignancies such as lung cancer (EGFR inhibitors) and melanoma (BRAF inhibitors)." (PMID 41228245, 2025). "Overall expression of mutant BRAF in melanoma was mean 141.61 ± 268.03 transcripts per million (TPM) (mean ± standard deviation) compared to 28.31 ± 17.9 in WT BRAF (p < 0.005)." (PMID 40869231, 2025). "In one investigation, plasma ctDNA BRAF V600E levels were measured using ddPCR in 8 controls and 20 patients with BRAF V600E-mutant advanced melanoma during BRAFi treatment." (PMID 39859576, 2025). "The combination use of BRAF and MEK inhibitors has become a standard first-line treatment for BRAF-mutant melanoma." (PMID 41355975, 2025). "The mTOR inhibitors rapamycin (sirolimus) and NVP-BEZ235 induce apoptosis and cell cycle arrest in BRAF mutant melanoma cell lines." (PMID 39941158, 2025). "Initial evidence supporting the efficacy of BRAF inhibition in thyroid cancer emerged from early clinical trials in melanoma, where dabrafenib showed high response rates in BRAF-mutant tumors." (PMID 41368991, 2025). "saw benefit with better relapse control with ATP kinase inhibitors dabrafenib & trametinib compared to PD-1 immunotherapy but specifically in BRAF-mutant melanomas." (PMID 41164124, 2025). "Two patients in the Ipi10 + TMZ cohort had a partial response, and both responders had BRAF V600E mutant melanoma." (PMID 40136348, 2025). "LA interfered with crucial melanoma cell survival processes by inhibiting the BRAF–MAPK signaling pathway." (PMID 39795195, 2025). "Targeted therapies such as BRAF inhibitors (BRAFis), including dabrafenib and vemurafenib, constitute a major advance in the treatment of BRAF-mutant melanoma, although resistance develops quickly." (PMID 39996721, 2025). "Preclinical studies have demonstrated its effectiveness in both in vitro and in vivo settings, notably in BRAF inhibitor-resistant melanoma cell lines and xenografts, where it induced apoptosis more effectively than combined MEK/PI3K inhibition." (PMID 41425251, 2025). "BRAF inhibitors have been shown to activate the Sonic Hedgehog Homolog pathway in melanoma, which in turn will upregulate PDGFRα, leading to the development of resistance to the inhibitor." (PMID 40574005, 2025). "Another example would be the AGK::BRAF fusion which is the most common BRAF 5′ partner in melanoma and adult lung cancers and present in 19% of pediatric patients with thyroid gland papillary carcinoma." (PMID 40111124, 2025). "In this systematic review and metanalysis of 8 studies, we found that adjuvant D + T is associated with a favorable RFS in comparison to anti-PD1s in patients with locally advanced BRAF mutant melanoma." (PMID 40758471, 2025).
melanoma (continued). "VEM, BRAF expression inhibitor, has been tested for the treatment of melanoma both in vitro and in vivo and has yielded positive results." (PMID 40076912, 2025). "The DREAMseq trial randomized patients with BRAF–mutant melanoma to receive either first-line ipilimumab plus nivolumab followed by dabrafenib plus trametinib upon progression, or the reverse sequence." (PMID 40332507, 2025). "Prior work has demonstrated cytotoxic and cytostatic effects of Hsp90 inhibitors in melanoma and even the ability to delay resistance to BRAF and MEK inhibitors." (PMID 40135438, 2025). "The rate in our data was consistent with reported percentages of BRAF V600E in melanomas seen in The Cancer Genome Atlas (TCGA) and AACR Genomics Evidence Neoplasia Information Exchange (GENIE) databases (35% [n = 480] and 21% [n = 7915], respectively)." (PMID 40869231, 2025). "Hyperglycaemia has also been associated with BRAF and MEK inhibition, with the incidence of grade III-IV hyperglycaemia ranging from 2 to 6% in melanoma and 46% in thyroid cancer." (PMID 39671021, 2025). "HDAC8 expression is upregulated in resistant BRAF-mutant melanoma cells, where HDAC8 deacetylates c-Jun to reactivate MAPK signaling." (PMID 39935431, 2025). "Genes central to the main female-biased cancers (melanoma, gastric and thyroid), breast cancer and ESR1, which encodes oestrogen receptor-α (ERα), include CDH1 (which encodes E-cadherin), CCND1 (cyclin D1), BRAF and KRAS." (PMID 40500450, 2025). "Recent findings have identified p38 MAPK as a novel mediator in the adaptive response of melanoma cells to BRAF-targeted therapy." (PMID 40872623, 2025). "This study highlights the impact of autophagy modulation on BRAF(V600E)-siRNA efficacy in A375 melanoma cells, emphasizing the role of HCQ in enhancing apoptosis, whereas TRE appeared to attenuate HCQ’s effect." (PMID 41170188, 2025). "In ERK-driven tumors, such as BRAF-mutant melanoma, cancer cells show a marked dependence on ERK2, with its inhibition leading to a substantial decrease in proliferation markers, an effect that is not reproduced by ERK1 silencing." (PMID 40723336, 2025). "Tovorafenib resulted in tumor regression in an AGK::BRAF fusion melanoma patient-derived xenograft model in vivo, while exhibiting little antitumor activity in NF1-LOF tumor models." (PMID 40111124, 2025). "Autophagy has been found to contribute to acquired resistance to targeted therapies in BRAF V600-mutant melanoma, which has led to interest in targeting autophagy pathways as a strategy to improve outcomes in BRAF V600-mutant melanoma." (PMID 40457397, 2025). "This is consistent with published data showing that preclinically the combination of type II RAF inhibitors and MEK inhibitors is synergistic in colorectal, melanoma, and lung tumor cell lines with mutations in NF1, BRAF, or KRAS." (PMID 40111124, 2025). "We present the case of a 67-year-old male with a history of wild-type BRAF V600E malignant melanoma of the left lower limb, status post resection three years prior, who presented for observation with known multi-system metastases." (PMID 41142597, 2025). "It is also important to recognize that concomitant BRAF and NRAS mutations are exceedingly rare in both melanoma and patients with CLL; therefore, it must be confirmed." (PMID 39940799, 2025). "This targeted, drug‐loaded tFNA downregulated mutant BRAF kinase and induced melanoma cell apoptosis." (PMID 39263835, 2025). "A more recent clinical study with 22 BRAF+MEK inhibitor-resistant BRAFV600-mutant melanoma patients revealed that the daily oral dose of 360 mg vorinostat was well-tolerated and showed an overall response rate of 9%, including one complete response." (PMID 39935431, 2025).
melanoma (continued). "The same trend holds for VEGF and HIF1a, where these genes are expressed with the expected range of values compared to historical melanoma cases with WT BRAF, but significantly higher in melanoma with BRAF V600E genotype." (PMID 40869231, 2025). "A total of 3515 single cells from fourteen patients with available genotyping information were analyzed: 1970 from wild-type melanomas, 1051 from NRAS Q61L melanomas, 226 from BRAF V600K melanomas, and 268 from BRAF V600E melanomas." (PMID 39796775, 2025). "La detección de dicha mutación en melanoma es auspiciosa ya que existen terapias dirigidas como los inhibidores de BRAF y MEK que han mejorado notablemente la supervivencia de los pacientes que la portan." (PMID 40977817, 2025). "While BRAF inhibitors (BRAFi) such as vemurafenib can offer temporary clinical benefits in patients with BRAF-mutant melanoma, the development of resistance remains a major therapeutic hurdle." (PMID 41403438, 2025). "Mechanistic investigations have revealed that the novel Pyrrolidine Diketopiperazines 2155-14 and 2155-18 induce ER stress, which enhances basal autophagy and ultimately leads to melanoma cell death in BRAF- and NRAS-mutated melanoma cells." (PMID 40331942, 2025). "Among other things, overactivation of the MEK 1/2-ERK 1/2 cascade in BRAF mutant melanoma cell lines led to significant cytotoxic effects." (PMID 40240755, 2025). "This breakthrough enabled the development of small-molecule inhibitors that selectively target mutant BRAF, fundamentally reshaping the therapeutic landscape of melanoma." (PMID 41302945, 2025). "Therapy resistance: AR signaling enables melanoma to evade targeted treatments such as BRAF/MEK inhibitors and diminishes the effectiveness of immune checkpoint blockade." (PMID 40940929, 2025). "Targeted therapies that block the BRAF/MEK molecular signalling pathway have improved the outcomes of BRAF‐mutant melanoma patients." (PMID 40936400, 2025). "Oncogenic forms of BRAF have been identified in many tumours, including malignant melanomas, colorectal cancer, lung, papillary thyroid, and ovarian neoplasms." (PMID 39941911, 2025). "ARV-825 effectively downregulates c-Myc expression, which resensitizes melanoma cells that are resistant to BRAF inhibitors, thereby producing synergistic cytotoxic, anti-migratory, and pro-apoptotic effects." (PMID 40284496, 2025). "HDACs are critically involved in cell survival processes, suppress apoptosis induction, and are correlated with BRAF inhibitor resistance in melanoma and other BRAF-mutant cancers." (PMID 39935431, 2025). "BRAFis such as vemurafenib and dabrafenib are highly effective in advanced BRAF V600E-positive melanoma, with a response rate of 60–80 %." (PMID 40977811, 2025). "The relatively small sample size, and particularly the low proportion of BRAF-mutant melanomas, limited the statistical power to conduct multivariable analyses or calculate reliable diagnostic performance metrics (AUC, sensitivity, specificity)." (PMID 41010758, 2025). "Targeted therapies, such as BRAF/MEK inhibitors in melanoma and TKIs, optimize ICI responses by modulating the TME and gut microbiome, which are key factors that improve ICI responses with certain bacterial strains that enhance antitumor immune activity." (PMID 40361336, 2025). "The BRAF mutational status is tested in advanced stages of melanoma due to the possibility of choosing between targeted therapy and immunotherapy in BRAF-mutant melanomas." (PMID 41010758, 2025). "Expressing Rac1 P29S in 451Lu cells, another BRAF V600-mutant human melanoma cell line, also promoted BRAFi-resistance that was partially dependent on PAK signaling, based on PAK inhibition by G-5555." (PMID 41109929, 2025). "RNA expression of BRAF and the 10 MAPK-associated genes were increased in melanomas with V600E compared to wild-type BRAF (p = 0.02)." (PMID 40869231, 2025).